TLR2 (toll like receptor 2)
Diseases named in the same sentence as TLR2 in open-access papers (continued):
Sharing a sentence is not in itself a finding about the gene and the disease.
Sepsis (continued). "During sepsis, exosomes contribute to the progression of inflammation by carrying proinflammatory cytokines (such as IL-1β, IL-6, TNF-α) and activating Toll-like receptors (TLR2, TLR4, TLR7) in immune cells." (PMID 41268545, 2025). "Additionally, silenced C5ar1 inhibited the TLR2, TLR4, and peptidylarginine deiminase 4 expression levels, which suggested the improvement of silenced C5ar1 on sepsis via inhibiting NETs and the TLR signaling pathway." (PMID 38165570, 2024). "TLR2 and TLR4 mRNA upregulation is also described in monocytes from patients with sepsis." (PMID 38835761, 2024). "Interestingly, Toll‐like receptor signalling was detected in sepsis, specifically in the brain (prefrontal cortex and hippocampus), via the upregulation of genes such as CD14, TLR1, TLR2, TLR3, TLR7, IRAK3 and IRAK4." (PMID 37731199, 2023). "Similarly, NETs-mediated fibrinogen deposition and TF expression in the lung were also significantly reduced in TLR2−/− mice group, accompanied by reduced STING activation, all indicating that sepsis-induced coagulation activation was attenuated." (PMID 37626060, 2023). "One study has reported that the expression of TNF-α was downregulated in Irak1-deficient macrophages when TLR2 or TLR4 were activated, thereby weakening the response to the lethal effects of sepsis caused by LPS or Gram-negative bacteria." (PMID 34421892, 2021). "Moreover, renal resident cells also expressed TLR, in particular TLR2 and TLR4, and actively participate in sepsis-induced AKI." (PMID 33868226, 2021). "In sum, the activation of TLR2, TLR4, TLR7, TLR9 and NLRP3 are almost certainly maintained by DAMPs in severe COVID-19, ALI/ARDS and sepsis and may need to be therapeutically addressed." (PMID 33672738, 2021). "The expressions of TLR2, TLR3, TLR4, and TLR7 increased in the kidneys and intestine of sepsis mice, indicating that these four cytokines could influence the effect of pro-inflammatory response during infection." (PMID 34938184, 2021). "Here, we show that TLR2, TLR4, CD36, P2RX7, VIMP, and SCARB1 are also expressed in myocytes and muscle and that muscular expression of TLR2, TLR4, CD36, and VIMP increases during sepsis." (PMID 31441598, 2020). "We found that exposure of human endothelial cells to LPS/PepG resulted in mitochondrial dysfunction and oxidative stress, associated with changes in expression of genes and selected proteins involved in TLR2 and TLR4 signalling and the inflammatory response to conditions of sepsis." (PMID 32110961, 2020). "However, NET formation was shown to be ROS(NOX)-independent in multiple settings including sepsis, and so was NET release induced by complement receptors, TLR2/TLR4 ligands or TLR4-activated platelets." (PMID 32010131, 2019). "As a synthetic ALX agonist, BML-111 could mitigate inflammatory response in the lung and intestinal mucosal barrier during sepsis by inhibiting the activation of the Akt, ERK1/2, and p38 MAPK signaling pathways and decreasing the expression of TLR2 and TLR4." (PMID 30186119, 2018). "Among all TLRs, TLR2, and TLR4 are the two notable contributors to the pathogenesis of sepsis." (PMID 28769820, 2017). "Additionally, it is also noteworthy that other TLRs, such as TLR2 and TLR4, present pivotal roles in the regulation of sepsis-induced cardiac inflammation during sepsis." (PMID 26448624, 2015). "In addition, TLR2 and CD14 were analyzed as representatives of the pattern-recognition receptors which represent another system that was upregulated in sepsis patients of the discovery set." (PMID 26607226, 2015). "Given its dual effects on TLR2 signaling pathway and inflammation, MFHAS1 might be a suitable novel therapeutic tool to achieve immune balance in sepsis." (PMID 26599367, 2015). "Our group and others have shown that blockade of TLR2 or TLR4 was successful in decreasing disease severity in sepsis models of Gram-negative and-positive bacteria, respectively." (PMID 26147469, 2015).
Sepsis (continued). "Contrary to TLR2- or TLR4-deficient mice, mice which are deficient in Myd88, a signalling module shared by many TLR receptors, failed to deal with mild or moderate sepsis and succumbed rapidly to infection." (PMID 26147469, 2015). "Indeed, our group has previously reported that TLR2, 4 and 9 play a deleterious role in CLP-induced severe sepsis." (PMID 25084278, 2014). "CEACAM1 is also reported to inhibit Toll-like Receptor-2 signaling and Toll-like Receptor-4, thus increased circulating soluble CEACAM1 might contribute to inhibition of Toll-like Receptor responses in sepsis." (PMID 23894299, 2013). "This study helps us to understand the specific mechanism of the signalling transduction of TLR2/2, TLR2/1 and TLR2/6, and it may provide us with novel clues to design targeted therapeutics against TLR2/2-, TLR1/2- and TLR2/6-induced sepsis." (PMID 23626692, 2013). "Consequently, endothelial cells are key players in sepsis, expressing toll-like receptor (TLR) 4 and TLR2, essential components of the innate immune system and pathogen recognition mechanisms." (PMID 23552565, 2013). "Thus, we showed that the innate immunity receptors TLR2 and TLR4 and the adapter protein MyD88 are important in the development of AKI secondary to sepsis." (PMID 22655058, 2012). "The aim of this study was to investigate the role of TLR2, TLR4 and MyD88 in sepsis-induced AKI." (PMID 22655058, 2012). "No haplotypes in TLR2, TRL4, TLR9, and MyD88 were associated with sepsis risk in this study (data not shown)." (PMID 21219635, 2011). "Using TLR3 agonist PolyI:C to induce IRF-7 in TLR2−/− mice, we found no increase in basal Ppargc1a mRNA levels, but we did rescue the Ppargc1a response in sepsis." (PMID 21966468, 2011). "As previously reported for ischemia-reperfusion injury, we found that administration of rhBCL2A1 failed to protect TLR2-null mice from sepsis-induced mortality, indicating that there is a requisite role for TLR2 signaling for the protective effect in vivo." (PMID 21390214, 2011). "Our results also indicated that tag SNPs of TLR2, TLR4, TLR9, and MyD88 did not represent major risk factors for sepsis development." (PMID 21219635, 2011). "Both allele and genotype distributions of the other 14 SNPs in TLR2, TLR4, TLR9, MyD88, and TOLLIP did not vary significantly between sepsis patients and healthy controls." (PMID 21219635, 2011). "As these receptors are responsible for recognizing components of gram-negative (TLR4) and gram-positive (TLR2) bacteria, they have become a major target to blunt the pro-inflammatory response in sepsis." (PMID 20707930, 2010). "To determine the effect of B. pseudomallei sepsis on TLR protein expression at the surface of peripheral blood cells, we compared the expression of CD14, TLR1, TLR2, and TLR4 on circulating monocytes and granulocytes of patients with melioidosis and healthy controls using FACS analysis." (PMID 17676990, 2007). "Thus, multifunctional therapeutic agents that simultaneously inhibit both TLR2 and TLR4 activation while killing bacteria may serve as a promising strategy to combat sepsis." (PMID 40963927, 2025). "Within 24 hours of meeting sepsis-3 criteria, there is a markedly mitigated inflammatory cytokine production ex vivo in response to TLR2, 4, and 7/8 ligands as well as to bacteria prototypical for evoking sepsis such as Gram-positive S. aureus and Gram-negative E. coli." (PMID 35981050, 2022). "6-Gingerol-treated mice also displayed lower mortality in polymicrobial sepsis induced by CLP by enhancing bacterial clearance in the peritoneum, blood, and organs (liver, spleen, and kidney) while also suppressing the generation of TNF-α and IL-6 in TLR2 and/or TLR4-stimulated macrophages." (PMID 36588685, 2022). "Moreover, feces EVs containing both Gram-positive and Gram-negative bacterial EVs are capable of inducing sepsis-like systemic inflammation and this effect is mediated through both TLR2 and TLR4, respectively." (PMID 34281154, 2021).
Sepsis (continued). "After the activation of TLR, HMGB1 could acetylate and trigger its translocation from the nucleus to the circulation and interact with a variety of target cell receptors (RAGE, TLR2, TLR4, etc.), stimulating the release of pro-inflammatory cyto-/chemokines and leading to inflammations and sepsis." (PMID 34938184, 2021). "In sum, all that can be said in general about innate activation in sepsis is that TLR2, TLR4, TLR5, TLR7 and NLRP3 can be, but are not necessarily, activated, while TLR9 may or may not be downregulated." (PMID 33672738, 2021). "Importantly, in acting as a receptor antagonist for TLR2/1, MALP-2 may attenuate TLR2/1-mediated platelet activation during sepsis and other clinical conditions that are a potent source of TLR-triggering ligands." (PMID 32858930, 2020). "However, this is the first study to compare the effects of single or combined administration of mAbs that block TLR2 or TLR4 with or without antibiotics in polymicrobial sepsis." (PMID 26147469, 2015). "The role of MFHAS1 in targeting TLR2 involved in sepsis has not been examined thus far." (PMID 26599367, 2015). "Furthermore, mammalian toll-like receptors (TLR)-dependent pathway is also found to involve in the process of sepsis-induced apoptosis, which was confirmed by several studies: (i) apoptosis of spleen DCs from CLP performed on TLR4−/−, TLR2−/−, and TLR2−/− TLR4−/− was inhibited." (PMID 25821827, 2015). "Three genes were differentially expressed in uncomplicated sepsis patients but not in severe sepsis; IL-8 expression was lower than healthy controls (p = 5.0×10−4, Mann Whitney), whereas TLR2 and TLR4 expression was higher (p = 0.013 and p = 0004, respectively, Mann Whitney)." (PMID 25343379, 2014). "TLR2 and TLR4 are potent initiators of the inflammatory and immune response, triggering intracellular signaling cascades that eventually result in the increase of the expression of pro-inflammatory cytokines, therefore playing an important role in sepsis pathogenesis." (PMID 23552565, 2013). "Interestingly we could show in our study a relatively lower receptor expression (CD14, TLR2 and as a trend in TLR4), in patients with sepsis that died, compared to patients that survived." (PMID 19371402, 2009). "Further investigations in the HMGB1-RAGE-TLR4/TLR2 axis in platelet activation using recombinant HMGB1 or platelet-derived HMGB1 and knockouts will be warranted in dogs considering that RAGE-dependent mechanisms may be central to the pathogenesis of thrombosis in sepsis." (PMID 34235204, 2021). "Moreover, it has been reported that histones and myeloperoxidase could be responsible for NET-induced endothelial dysfunction, and histones can also interact with TLR2 and TLR4 to induce cytokine production via MyD88 signaling, contributing to the systemic inflammatory response observed in sepsis." (PMID 27199981, 2016). "Our results demonstrate that blockade of either TLR2 or TLR4 significantly decrease systemic inflammatory responses and lethality especially when used in combination with antibiotics, representing a specific preclinical setting at which blockers of TLR may be useful in patients with sepsis." (PMID 26147469, 2015). "Finally, we determined that expression of TLR2 and TLR4 is mostly intracellular in circulating human NK cells and that these receptors are upregulated differentially in and on NK cells of SIRS and sepsis patients, allowing discrimination of these two groups of patients." (PMID 23098236, 2012). "Absence of TLR2 and TLR4 improved cardiac function after ischemia/reperfusion (I/R) injury and during sepsis in mice and ameliorated impaired cardiac calcium handling in presence of extracellular histones." (PMID 36131923, 2022). "Murine models of sepsis-induced ALI mimic TLR3, TLR4, TLR7 and NLRP3 activation but, unlike the human disease, also activate TLR2 and TLR9." (PMID 33672738, 2021).
Sepsis (continued). "In patients with neutropenic fever, levels of mRNA expression of TLR2 and TLR4 were significantly higher in sepsis patients compared to patients without sepsis." (PMID 30796468, 2019). "Upregulation of TLR2 and TLR4 in response to the presence of PAMPs has extensively been studied in non-sterile inflammatory conditions like sepsis and septic shock." (PMID 27260481, 2016). "We demonstrate that the mRNA expression of TLR2 and TLR4 before induction chemotherapy was significantly higher in septic patients than in patients without sepsis symptoms." (PMID 25412934, 2014). "In patients with neutropenic fever, the mRNA expression of TLR2 and TLR4 was significant higher in septic patients than in patients without sepsis symptoms (ΔCt TLR2 0.93 ± 0.82 vs 0.78 ± 0.85 and ΔCt TLR4 0.38 ± 0.29 vs 0.34 ± 0.25)." (PMID 25412934, 2014). "Among the patients with neutropenic fever, the mRNA expression of TLR2 and TLR4 was significantly higher in septic patients than in patients without sepsis symptoms." (PMID 25412934, 2014). "Furthermore, in patients with acute myeloid leukemia, mRNA expression of TLR2 and TLR4 was found to be considerably higher in those with sepsis than in those without symptoms of sepsis prior to induction chemotherapy." (PMID 38685971, 2024). "Moreover, blockade of TLR2 and TLR4 signaling by antagonistic antibodies successfully decreases disease severity in sepsis models of Gram-positive and Gram-negative bacteria, respectively." (PMID 28769820, 2017). "While TsES did not affect expression of TLR2 and TLR4 during sepsis, it might still regulate other TLR expressions and should be further investigated." (PMID 25054155, 2014). "As we used a model of polymicrobial (gram-positive and-negative) sepsis, changes in CD14 expression, increased by TLR4- and/or TLR2-mediated signaling, may reflect infection with both gram stain groups." (PMID 23302299, 2013). "To determine whether the absence of TLR2, TLR4 and MyD88 affects the mortality in AKI induced by CLP, we evaluated the survival of all mice for 192 hours after the induction of sepsis." (PMID 22655058, 2012). "As shown in our study, an inadequate downregulation of TLR2 and CD14 (and consecutive reduced cytokine release) during sepsis might have a negative influence on outcome." (PMID 19371402, 2009). "Taken together, these data suggest that a reduced TLR2 and CD14 expression during sepsis might have a negative outcome in sepsis." (PMID 19371402, 2009). "In contrast, the concentration of IL-10 in sepsis patients significantly increased even beyond values seen in samples from healthy subjects following stimulation with the TLR4 ligand (p = 0.0036), but not significantly following stimulation with TLR2 or 7/8 ligands." (PMID 35981050, 2022).
colitis (164 papers, 2007 to 2026). Inflammation of the colon. "Intrarectal administration of 50% ethanol and PGN causes TLR2-dependent experimental colitis, characterized by a Th1 response." (PMID 39403381, 2024). "Resistance to TLR2-dependent colitis in NOD2-transgenic mice is associated with a diminished Th1 response." (PMID 39403381, 2024). "TLR2-deficient mice show impaired barrier function and more severe colitis when infected with Campylobacter jejuni." (PMID 38164397, 2023). "TLR2 knockdown significantly inhibited proliferation of the CRC cells but exacerbated colitis symptoms in the mouse colitis-associated cancer model (CAC)." (PMID 37191444, 2023). "Studies in SPF WT and TLR2−/− mice show that purified PSA prevented and reversed TNBS-induced colitis in a TLR2-dependent manner associated with the induction of FoxP3+ cells." (PMID 32133003, 2020). "TLR9-deficient mice were highly susceptible to experimental colitis and had a lower NF-κB activation threshold when compared to wild-type and TLR2-deficient mice." (PMID 32661259, 2020). "Recently, a study from our laboratory showed that TLR2 deficiency contributes to the impaired innate immune defense and high susceptibility to colitis in mice by changing IELs." (PMID 31040849, 2019). "Our current study effectively shows that human commensal B. fragilis utilized TLR2 for its protective role against the development of colitis-associated colon cancer in accordance with previous reports." (PMID 30429227, 2018). "This is consistent with a previous result showing that TLR2-deficient mice were susceptible to colitis-associated CRC." (PMID 30429227, 2018). "It was reported previously that TLR2 signaling is important for the anti-inflammatory response of B. fragilis in intestinal inflammation and that TLR2 plays a protective role against the development of colitis-associated CRC." (PMID 30429227, 2018). "The aim of this study is to investigate how TLR2 affects differentiation of intraepithelial lymphocytes (IELs) and regulates the susceptibility of colitis." (PMID 27563173, 2016). "Our results also indicate that deficiency of TLR2 contributes to the high susceptibility of mice to dextran sulfate sodium- (DSS-) induced colitis." (PMID 27563173, 2016). "In a Citrobacter rodentium–induced colitis model, TLR2-deficient mice exhibited 45 to 75% mortality coincident with severe defects in TJ-associated IEC integrity." (PMID 25915861, 2015). "Consistently, TLR2-deficient mice are more susceptible to dextran sodium sulfate (DSS) induced colitis." (PMID 26067254, 2015). "The increased susceptibility to DSS colitis exhibited by TLR2−/− mice can be abrogated by treatment with GDNF." (PMID 25309051, 2014). "The TH17 skewing that we have observed in TLR2-deficient mice in the context of colitis-induction in this study is consistent with recent findings linking IL-17 and IL-23 variants with increased susceptibility to IBD." (PMID 20885960, 2010). "Our results reveal for the first time that the induction of colitis or ileitis in mice is associated with marked increases in the luminal concentrations of PAMPs specific for TLR2, TLR4 and/or TLR5." (PMID 20161736, 2010). "In the absence of TLR2, we observed greater tumor incidence, tumor numbers and tumor sizes in a model of colitis-associated colon cancer, providing evidence for the critical role TLR2 plays in protection from CAC development and progression." (PMID 20885960, 2010). "Based on our observations that TLR2-deficient mice exhibit unregulated proliferative growth and ignorance of apoptotic signals during colitis, we describe a new and critical role for TLR2-induced protection from epithelial transformation." (PMID 20885960, 2010). "To examine the role of TLR2 during colitis-associated tumorigenesis we used a well established model of CAC." (PMID 20885960, 2010).